MDM2 (MDM2 proto-oncogene)
Diseases named in the same sentence as MDM2 in open-access papers (continued):
Sharing a sentence is not in itself a finding about the gene and the disease.
myelofibrosis (3 papers, 2023 to 2026). A partial or complete replacement of the bone marrow stroma by fibrous tissue. "A few studies demonstrated that in patients with myelofibrosis who received ruxolitinib or navtemadlin (a MDM2 inhibitor) circulating CD34-positive cells decreases progressively during treatment." (PMID 41540281, 2026).
oligodendroglioma (3 papers, 1997 to 2016). A well-differentiated (WHO grade II), diffusely infiltrating neuroglial tumor, typically located in the cerebral hemispheres.
osteoarthritis (3 papers, 2020). A noninflammatory degenerative joint disease occurring chiefly in older persons, characterized by degeneration of the articular cartilage, hypertrophy of bone at the margins and changes in the synovial membrane. "Indeed, recent findings show that UBX0101, an inhibitor of MDM2, selectively killed some SnCs in culture and effectively cleared them in mice with post‐traumatic osteoarthritis." (PMID 32064756, 2020). "Therefore, MDM2 inhibitors may be best for clearing SnCs to treat age‐related diseases such as osteoarthritis via local administration." (PMID 32064756, 2020).
psoriasis (3 papers, 2021 to 2024). An autoimmune condition characterized by red, well-delineated plaques with silvery scales that are usually on the extensor surfaces and scalp. "In contrast to the control samples, the mRNA expression of the mdm2 genes increased significantly in samples from patients with psoriasis at three time points." (PMID 35008548, 2021). "For immune cells, T cells and Monocytes were related to PEBP1, MDM2, TIMM9 and DCAF7 in psoriasis group." (PMID 36685512, 2022).
pterygium (3 papers, 2020 to 2025). A wedge-shaped fibrovascular lesion arising from the bulbar conjunctiva and extending to the cornea. "Further studies are required to evaluate the use of Nutlin and other MDM2 antagonists for the non-surgical treatment of pterygium." (PMID 37509256, 2023).
rectum adenocarcinoma (3 papers, 2022 to 2025). An adenocarcinoma arising from the rectum. "Heterozygous amplifications of ETS2 and CDK6 in TGCT; CDK6 in GBM; E2F1 and ID1 in rectum adenocarcinoma (READ); and SP1, CDK4, and MDM2 in ACC were all greater than 70%." (PMID 35911954, 2022). "To further understand this regulation, we analyzed 151 samples from The Cancer Genome Atlas rectum adenocarcinoma (TCGA-READ) database (portal.gdc.cancer.gov/) and found that the mRNA expression level of PXR negatively correlated with mRNA expression of MDM2 (p < 0.05)." (PMID 35372071, 2022).
renal fibrosis (3 papers, 2022 to 2025). A final common manifestation of a wide variety of chronic kidney diseases characterized by glomerulosclerosis and tubulointerstitial fibrosis. "Histological analysis via PAS and Masson's trichrome staining revealed that MDM2 silencing significantly reduced renal fibrosis." (PMID 40421968, 2025). "Thus, future functional studies should further clarify the potential role of hsa-miR-484 in renal fibrosis and mechanisms of interaction and regulation between MDM2 and NOTCH signalling, which may represent potential pharmacological targets for prevention and treatment." (PMID 36273030, 2022).
salivary gland carcinoma (3 papers, 2012 to 2022). A carcinoma that arises from the major or minor salivary glands. "The aim of this study was to determine whether genetic variants in MDM2 and p14ARF are associated with risk of salivary gland carcinoma (SGC)." (PMID 23145162, 2012).
salivary gland neoplasm (3 papers, 2009 to 2025). Tumors of the SALIVARY GLANDS. "From the literature search a total of five studies detailing 19 cases of HMGA2-altered, MDM2-analyzed salivary gland neoplasms were included." (PMID 40338436, 2025). "Combining the cases derived from literature and the additional cases from our clinical practice, a total of 37 HMGA2-altered salivary gland neoplasms analyzed for MDM2 amplifications were collected for this analysis." (PMID 40338436, 2025). "In conclusion, we found that immunohistochemical MDM2 expression and MDM2 amplifications are frequent in HMGA2-altered salivary gland tumors with cytonuclear atypia, potentially playing a role in the progression towards malignancy." (PMID 40338436, 2025). "The present study aims to investigate the immunohistochemical expression of murine double minute-2 (mdm-2), p27Kip1 and B cell lymphoma-2 (bcl-2) in Warthin's tumor of parotid gland and also to clarify the role of these proteins in the behavior of that tumor." (PMID 19445705, 2009). "This study was aimed to investigate the immunoexpression of mdm2 oncoprotein, p27Kip1 tumor suppressor protein as well as bcl-2 anti-apoptotic protein in Warthin's tumor as a trial to clarify the possible role of these families in the pathogenesis of this unique tumor of salivary glands." (PMID 19445705, 2009). "Due to the enriched presence of MDM2 amplification in CXPA with HMGA2 alteration, recognition of this molecular sub-group of salivary gland neoplasms could be potentially informative in the pathologists’ assessment." (PMID 40338436, 2025). "The exact relationship between MDM2 and HMGA2 alterations in salivary gland neoplasms remains unclear, however, we propose a potential mechanism." (PMID 40338436, 2025).
small cell lung carcinoma (3 papers, 2020 to 2025). Small cell lung cancer (SCLC) is a highly aggressive malignant neoplasm, accounting for 10-15% of lung cancer cases, characterized byrapid growth, and early metastasis. "Alternatively, the direct targeting of the proto-oncogenic E3 ligase Mdm2 is the basis of the anti-infective drug nitroxoline (NXQ), which is potentially useful for therapy of small cell lung cancer." (PMID 39851496, 2025).
type 2 diabetes (3 papers, 2013 to 2018). "This is consistent with our previous works showing some alterations of Mdm2 expression or activation in rodent models of type-2 diabetes and limb ischemia." (PMID 24303114, 2013).
viral hepatitis (3 papers, 2011 to 2021). An acute or chronic inflammation of the liver parenchyma caused by viruses. "In conclusion, these results provide the first evidence that the MDM2 SNP309 polymorphism represents a risk factor for viral hepatitis-related HCC in the Italian population." (PMID 21843334, 2011).
Alzheimer’s disease (2 papers, 2016 to 2023). A progressive, neurodegenerative disease characterized by loss of function and death of nerve cells in several areas of the brain leading to loss of cognitive function such as memory and language. "Based on its high proximity to AD related genes, another important player in AD is MDM2 which is directly connected to eleven already known Alzheimer’s disease genes." (PMID 26784894, 2016).
anaplastic astrocytoma (2 papers, 2008 to 2015).
angiomyolipoma (2 papers, 2019 to 2025). A neoplasm with perivascular epithelioid cell differentiation often associated with tuberous sclerosis. "In our case, these markers stained positive, whereas nuclear stains for MDM-2 as well as for HMB45 and Melan-A were negative, characteristic markers when positive for angiomyolipoma." (PMID 30611280, 2019).
B-Acute Lymphoblastic Leukemia (2 papers, 2016 to 2023).
bladder tumor (2 papers, 2011 to 2021).
brain cancer (2 papers, 2023). A primary or metastatic malignant neoplasm affecting the brain. "Thirdly, the UALCAN database was utilized to assess the MDM2 gene promoter methylation level in brain cancer, where the methylation status is exhibited as a beta value scale." (PMID 37049742, 2023). "According to the UALCAN database, the amount of mRNA produced by the MDM2 gene was shown to be significantly higher in TCGA brain cancer samples." (PMID 37049742, 2023). "Following that, the genetic alteration appearance of the MDM2 gene was examined utilizing data from several brain cancer studies." (PMID 37049742, 2023). "Likewise, MDM2 gene overexpression was investigated in several clinical phases of brain cancer." (PMID 37049742, 2023).
Cerebral ischemia (2 papers, 2018 to 2022). Restriction of arterial blood supply to the brain associated with insufficient oxygenation to support the metabolic requirements of the tissue.
chronic hepatitis C (2 papers, 2011). "In Eastern Asia MDM2 SNP309 G allele has been associated with higher risk of HCC in Japanese patients with chronic hepatitis C, in Korean patients with chronic HBV, and in Taiwanese patients infected with HBV or HCV infection." (PMID 21843334, 2011).
clear cell carcinoma (2 papers, 2016 to 2021). "In conclusion, we demonstrated that MDM2 is frequently overexpressed in clear cell carcinomas, and that MDM2 overexpression is associated with poor prognosis." (PMID 27659536, 2016). "MDM2 expression was significantly higher in clear cell carcinoma than in ovarian high-grade serous carcinoma (P = 0.0092) and normal tissues (P = 0.035)." (PMID 27659536, 2016). "Next, the antiproliferative effect of RG7112, an MDM2 inhibitor, was evaluated in these clear cell carcinomas." (PMID 27659536, 2016). "Clear cell carcinomas were further stratified as MDM2-high (n = 25), MDM2-intermediate (n = 25), and MDM2-low (n = 25)." (PMID 27659536, 2016). "Taken together, the data provide a strong rationale to target MDM2 in clear cell carcinoma." (PMID 27659536, 2016). "Our results highlight the prognostic value of MDM2 expression in clear cell carcinoma." (PMID 27659536, 2016). "MDM2 expression was higher in 61 of 75 (81%) clear cell carcinomas than in normal ovarian tissue." (PMID 27659536, 2016). "Indeed, MDM2 expression was significantly higher in clear cell carcinomas than in normal tissues (P = 0.035) and high-grade serous carcinomas (P = 0.0092)." (PMID 27659536, 2016). "Therefore, MDM2 might be a more suitable target than MDM4 in clear cell carcinomas." (PMID 27659536, 2016). "Nevertheless, whether MDM2 and/or MDM4 are overexpressed in clear cell carcinoma remains to be established, along with whether MDM2 inhibitors are active against these forms of cancer." (PMID 27659536, 2016).
colorectal tumors (2 papers, 2008 to 2021).
desmoid tumor (2 papers, 2023 to 2024). A desmoid tumor (DT) is a benign, locally invasive soft tissue tumor associated with a high recurrence rate but with no metastatic potential. "There is no direct study about the association between desmoid tumors and MDM2; however, our lab recently obtained a human desmoid tumor cell line with loss-of-function screening using an shRNA pool and we found some essential genes that are important for desmoid tumor cell growth." (PMID 37297833, 2023). "Overall, these data suggest that MDM2 is also important for the progression of desmoid tumors." (PMID 37297833, 2023). "There is some non-direct evidence that targeting MDM2, or its specific downstream target, making MDM2 a potential therapy for human desmoid tumors." (PMID 37297833, 2023).
diabetic cardiomyopathy (2 papers, 2016 to 2023). Diabetic cardiomyopathy is a disorder of the heart muscle in people with diabetes.
Diamond-Blackfan anemia (2 papers, 2012 to 2018). A congenital aregenerative and often macrocytic anemia with erythroblastopenia.
esophageal tumor (2 papers, 2010 to 2025). "Markers such as CK, P40, and P16 effectively excluded common epithelial cell-derived esophageal tumors, while negative staining for SMA, desmin, and MDM2 further supported the differential diagnosis." (PMID 40636370, 2025).
giant cell tumor of bone (2 papers, 2018 to 2022). "In our previous study, mouse double minute 2 homolog (MDM2), insulin-like growth factor 1 (IGF1), signal transducer and activator of transcription 1 (STAT1), and Rac family small GTPase 1 (RAC1) were correlated with the recurrence of giant cell tumor of bone (GCT)." (PMID 29651441, 2018).
glaucoma (2 papers, 2018 to 2024). Increased pressure in the eyeball due to obstruction of the outflow of aqueous humor.
hepatitis B (2 papers, 2014 to 2018).
hepatoblastoma (2 papers, 2023). Hepatoblastoma (HB) is a malignant hepatic tumor and is the most common pediatric liver cancer. "The interaction between MDM2 and MDMX is targeted through small molecule NSC207895 in hepatoblastoma which inhibited MDMX ability to upregulate MDM2." (PMID 37314603, 2023).
idiopathic pulmonary fibrosis (2 papers, 2018 to 2024). Idiopathic pulmonary fibrosis (IPF) is a nonneoplastic pulmonary disease that is characterized by the formation of scar tissue within the lungs in the absence of any known cause. "Among them, nintedanib, an FDA-approved multikinase inhibitor for Idiopathic Pulmonary Fibrosis (IPF), showcased the potential as a new MDM2/MDMX dual inhibitor, and this was validated by a series of structural and biochemical analyses." (PMID 38059334, 2024). "The levels of MDM2 (RING-type) and FIEL1 (HECT-Type E3) are increased in lung tissues from patients with idiopathic pulmonary fibrosis (IPF)." (PMID 30386338, 2018).